GRP (gastrin releasing peptide)
Diseases named in the same sentence as GRP in open-access papers (continued):
Sharing a sentence is not in itself a finding about the gene and the disease.
cancer (58 papers, 2004 to 2025). A tumor composed of atypical neoplastic, often pleomorphic cells that invade other tissues. "Although further efforts will be made to highlight the relevance of GRP in cancer processes, we showed that GRP is associated with pathological mineralization in cancer and has the in vitro capacity to directly interact with calcium crystals." (PMID 24949434, 2014). "Gastrin-releasing peptide (GRP) is a neuroendocrine peptide that belongs to a bombesin-like peptide family found in mammals and has been associated with cancer development." (PMID 41266536, 2025). "GRP is involved in the mitogenesis of cancer cells, and it also has paracrine and endocrine effects." (PMID 38806963, 2024). "GRP is over-expressed in a number of cancers including lung, breast, stomach, pancreas, renal, prostate, and colon." (PMID 36389725, 2022). "BN is a peptide that can specifically interact with local receptors on cancer cells, called gastrin-releasing peptides (GRP)." (PMID 35890220, 2022). "Gastrin-releasing peptide (GRP) is a neuroendocrine peptide with stimulating effects in the proliferation of certain types of cancer." (PMID 34068618, 2021). "GRP is regarded as a growth factor of cancer which regulates cancer cell motility by mediating its morphogenic properties." (PMID 33996273, 2021). "This provides a rationale for using the MME/GRP pathway for targeting of cancer-propagating cells, perhaps as a part of combinatorial therapy approaches." (PMID 32205838, 2020). "The GRP-PVP-NP nanosheets served as a nano-carrier for anti-cancer drugs due to the advantage of a high surface area with drugs adhere on both sides of the single sheet." (PMID 28858235, 2017). "The toxic effect of graphene-poly(vinylpyrrolidone) nanoparticle composite (GRP-PVP-NP) against cancer cells is visualized." (PMID 28858235, 2017). "Further, GRP acts as a mitogen, morphogen and pro-angiogenic factor in certain cancers, including PC." (PMID 27542219, 2016). "Patterns of γ-carboxylated GRP (cGRP)/undercarboxylated GRP (ucGRP) accumulation in healthy and cancer tissues were determined by immunohistochemistry, using newly developed conformation-specific antibodies." (PMID 24949434, 2014). "Previous studies ascertaining the efficacy of GRP antagonists in cancer have focused on its mitogenic property with the aid of subcutaneous xenograft models." (PMID 24039782, 2013). "Though GRPR is overexpressed in many solid tumors, only one other group has evaluated GRPR, GRP and/or their gene product levels in surrogate tissues of cancer patients to date." (PMID 22296774, 2012). "Gastrin-releasing peptide (GRP) is involved in cancer growth and GRP receptors are expressed in a variety of cancer cells and have limited distribution in normal human tissue." (PMID 22228887, 2011). "Previous studies have shown that antagonists of bombesin/gastrin-releasing peptide (GRP) inhibit the growth of various cancers by interfering with the growth-stimulatory effects of bombesin-like peptides, and reducing the levels of epidermal growth factor." (PMID 14710236, 2004). "GRP, gastrin-releasing peptide, mainly regulates numerous functions of the gastrointestinal and central nervous systems and plays an important role in human various cancers." (PMID 31781593, 2019). "Special attention should be given to the suggested therapeutic effect of vitamin K on cancer progression and to the potential detrimental effects of vitamin K antagonists widely used in therapy of patients with cancer, on the functionality of VKDPs present in tumor tissues such as GRP and MGP." (PMID 24949434, 2014).
cancer (continued). "Therefore, the identification of new vitamin K targets in cancer, such as GRP, may contribute to unveil the role and functional mechanism of vitamin K in cancer development." (PMID 24949434, 2014). "Compared to primary cancer samples, genes such as GLYATL2, EDIL3, MEG3, FABP4, ASCL1, GRP, and WDFY4 were highly upregulated in CRPC, with statistically significant differences underscoring their potential roles in driving the castration-resistant phenotype." (PMID 40165961, 2025). "Gastrin Releasing Peptide (GRP), acting synergistically to promote cell proliferation, play an essential role in cancer development and are frequently over-expressed in various tumors." (PMID 35748788, 2022). "Other GPCR ligands such as LPA, prostaglandins, bradykinin, gastrin-releasing peptide (GRP), and bombesin (BN) can also transactivate EGFR to induce cancer proliferation, survival, and invasion." (PMID 33746610, 2021). "In both approaches cancer-propagating cells isolated from DU145, PC3, and LNCaP cells were increased in number after GRP treatment." (PMID 32205838, 2020). "For this patient, 6 CTCs were detected by NE‐FISH; however, serum cancer markers including CEA, CA 125, CYFRA 21‐1, NSE, SCC, and Pro‐GRP were normal." (PMID 31132233, 2019). "Cancer cells produce and secrete the neuropeptides CCK/gastrin, GRP and NMB, bradykinin, and vasopressin." (PMID 29262666, 2017). "FAK activation at Y397 site by GRP is well established in 293 HEK cells and various other cancer types." (PMID 23211542, 2012). "GRP, the mammalian analogue of BBS, is a growth factor that promotes cell proliferation in cancer cells." (PMID 23211542, 2012). "CEA: carcinoembryonic antigen; CYFRA: cytokeratin 19 fragment; Pro-GRP: pro-gastrin-releasing peptide.*Paratracheal lymph nodes were enlarged but confirmed negative.**Second cancer (adenocarcinoma) was detected.***Lung tumor appeared." (PMID 40698218, 2025). "The bombesin (Bn) receptor family [Gastrin-releasing peptide (GRPR/BB2R) and Neuromedin B receptors (NMBR/BB1R)] are G-protein coupled receptors (GPCR’s) with potent growth effects on normal tissues/numerous cancers, often by transactivating the ErbB receptor-tyrosine kinase (RTK) family." (PMID 41007372, 2025). "We found that the cancer subtype markers (GRP, CHGB, NEUROD1, and CHGA for NET; KRT5, DSC3, KRT6B, TP63, and KRT6A for SCC; and NKX2-1, KRT7, NAPSA, and MUC1 for ADC) were specifically expressed in the corresponding cancer subtypes." (PMID 35962452, 2022). "In vitro studies showed that the pro-GRP-loaded NBs can attach to SCLC cells with high affinity of the cells, indicating that targeting NBs not only have the ability to carry antibody but also are able to deliver the antibody to recognize the cancer cells." (PMID 29100457, 2017). "Interestingly, also other members of the neuromedin family of neuropeptides, such as neuromedin B (NMB) and gastrin releasing peptide (GRP), have been identified as cancer-promoting factors in human tumors." (PMID 28423716, 2017). "They observed high expression of both GRP and GRPR in the majority of cancers (62%), while normal adjacent tissues did not exhibit significant expression." (PMID 38279185, 2024).
psychiatric disorder (7 papers, 2007 to 2025). A disorder characterized by behavioral and/or psychological abnormalities, often accompanied by physical symptoms. "Thus, if deficiencies in GRP support aberrant dopaminergic signaling and enhanced salience at the time a fear memory is acquired, it may serve as an important marker for the long-term susceptibility to protracted fear responses and mental illness." (PMID 39580604, 2025). "Alterations in GRP or GRPR expression or function have been reported in patients with neurodegenerative, neurodevelopmental, and psychiatric disorders." (PMID 34301297, 2021). "Increasing evidence indicates that bombesin (BB)-like peptides (BLPs), such asthe gastrin-releasing peptide (GRP) and its receptor (GRPR), might play a rolein neurological and psychiatric disorders." (PMID 29213377, 2007).
infection (6 papers, 2017 to 2023). The state of being infected such as from the introduction of a foreign agent such as serum, vaccine, antigenic substance or organism. "In most varieties, in the first stage of infection (24 hpi), the upregulation of GRP expression occured, while downregulation was observed only in the sensitive variety—PR39F58." (PMID 34468910, 2021). "We discovered three gel spots that corresponded with secreted glycine-rich (GRP; spots 1897 and 1945) and glycine-proline rich (spot 5154) proteins that were accumulated in response to the infection." (PMID 31234913, 2019). "The Arabidopsis GRP AtGRP7 is targeted for ADP‐ribosylation by the Pseudomonas syringae effector HopU1, and Arabidopsis grp7 mutants are more susceptible to infection by this bacterial pathogen than wild‐type plants." (PMID 27696417, 2017). "However, the increased infection observed in the presence of soluble LRR17 was reversed by the incubation with anti-GRP, reinforcing that the GRP78 protein on the macrophage surface mediated the effect of LaLRR17." (PMID 37553284, 2023). "The amount of GRP- and RFP- LC3 puncta was quantified and the RFP-LC3 puncta was significantly more than GFP-LC3 puncta at 40 h post infection." (PMID 32943650, 2020).
GRP also shares sentences with these, for which no sentence is quoted: adenocarcinoma (9 papers); metabolic disorders (5); benign tumors (3); cardiovascular disease (3); lymph node metastasis (3); Medullary thyroid carcinoma (3); anemia (2); endothelial dysfunction (2); gastrointestinal disease (2); lung adenocarcinoma (2); lung squamous cell carcinoma (2); multiple myeloma (2); pancreatic (2); tuberculosis (2); acute pancreatitis (1); Anorexia (1); anxiety disorder (1); astrocytoma (1); atrophic gastritis (1); bladder cancer (1); blood cancer (1); carcinoid (1); carcinoid tumour (1); carcinoma in situ (1); chronic obstructive pulmonary disease (1); Cognitive impairment (1); COVID-19 (1); depression (1); endocrine disorders (1); fibrosis (1).
A further 36 diseases each share a sentence with GRP in 1 paper.